FNDC11 (fibronectin type III domain containing 11)
Synonyms: C20orf195; MGC5356
Tractability: No criterion of Open Targets' tractability assessment is met for any kind of drug.
Gene: Protein-coding gene on chromosome 20 (63,547,891 to 63,558,138, forward strand). Ensembl gene ENSG00000125531.
Subcellular location (Human Protein Atlas): Nucleoplasm; Vesicles; Aggresome
Gene Ontology:
Molecular function: protein binding
Genetic constraint (gnomAD): Loss-of-function variants: 18 observed, 20.41 expected, observed/expected ratio (o/e) 0.88, 90% interval 0.61 to 1.31. The upper end of that interval is the gene's LOEUF score, 1.31, which puts it in group 5 of 6, group 1 being the genes least tolerant of losing a copy. Missense variants: 413 observed, 439.41 expected, observed/expected ratio (o/e) 0.94, 90% interval 0.87 to 1.02. Synonymous variants: 189 observed, 198.23 expected, observed/expected ratio (o/e) 0.95, 90% interval 0.85 to 1.08.
Homologues: Orthologues: chimpanzee FNDC11 (99% identical), macaque FNDC11 (96% identical), pig FNDC11 (83% identical), dog FNDC11 (82% identical), mouse Fndc11 (81% identical), rat Fndc11 (81% identical), guinea pig FNDC11 (80% identical), tropical clawed frog fndc11 (35% identical).